EGFR (epidermal growth factor receptor)
Diseases named in the same sentence as EGFR in open-access papers (continued):
Sharing a sentence is not in itself a finding about the gene and the disease.
tumor (continued). "EGFR-mutant patients generally have a low response to anti-PD-1/PD-L1 treatment, by mechanisms not yet well understood, but investigations suggest that this resistance is due to low PD-1 expression associated with low tumor mutational burden (TMB)." (PMID 37895255, 2023). "In addition to the BDNF/TrkB axis, the EGFR signaling pathway is associated with tumor cell proliferation, angiogenesis, tumor invasion and metastasis, and apoptosis inhibition." (PMID 37928267, 2023). "EGFR signaling, which involves the mTOR pathway, is expressed in these tumors, and it is associated with tumor proliferation, invasive behavior, lower total resection, and epithelial-to-mesenchymal transition; this latter is also mediated by the ADAM12 metalloprotease." (PMID 37958702, 2023). "Yet, the cases with EGFRm+ NSCLCs with concomitant de novo high-level MET amplification at baseline may suggest tumor polyclonality, including heterogeneous clones with either mutated EGFR or amplified MET as a driver." (PMID 37685884, 2023). "In addition to EGFR amplification, mutations were also included to demonstrate their relationship with tumor localization." (PMID 37744696, 2023). "Several reports have shown that sE-cad inhibits apoptosis and has an important function in cancer progression via activation of several signaling cascades linked to tumor progression, such as the EGFR and IGF-1R signaling pathways, and consequent activation of ERK1/2 and PI3K signaling." (PMID 37760996, 2023). "Overall, VEGF was highly expressed in the tumor specimens with EGFR mutations." (PMID 37605832, 2023). "Given the recognised influence of EGFR gene mutations on the components of the tumour immunity in the microenvironment in NSCLC, we investigated whether the accumulation of pleural CD39 + CD8 + T cells was associated with the EGFR status in LUAD-related MPE." (PMID 38087217, 2023). "However, EGFR is a featured NSCLC driver with a high mutation rate and sensitive mutations of EGFR are almost always clonal events that involve in tumor initiation and development." (PMID 37634047, 2023). "Among 128 patients tested, 16 (12.5%) had EGFR mutations detected with either technique by formalin-fixed paraffin-embedded (FFPE) tumor tissue or/and serum circulating tumor DNA using next-generation sequencing, and 6 (4.7%) had ALK rearrangement by FFPE tumor tissue." (PMID 37009936, 2023). "However, to further enlighten the role of PD-L1 expression on the EGFR pathway in cancer, the EGFR mutations that are most relevant in terms of tumor growth should also be studied." (PMID 38152616, 2023). "Clinical and preclinical studies indicated the efficacy and safety of multiple therapies for NSCLC patients with different aberrations, including EGFR exon 19 deletions or exon 21 (L858R) mutations, RET fusion-positive metastatic, ALK genomic tumor aberrations, EGFR exon 20 insertions." (PMID 37568193, 2023). "In this study, we retrospectively identify the significance of the occurrence of EGFR mutations by assessing life expectancy, neurological symptoms in the disease course, and neuroimaging (to assess neoplasm and edema volume measured on FLAIR sequences) in a cohort of 81 surgically treated patients." (PMID 37240478, 2023). "EGFR vIII is a deletion mutation that generates a novel extracellular tumor-specific epitope." (PMID 37046332, 2023). "Besides this, novel therapeutic approaches based on molecular tumor markers were developed like the targeting of epidermal growth factor receptor (EGFR), a highly upregulated receptor in HNSCC associated with poor prognosis." (PMID 37455825, 2023).
tumor (continued). "Previous studies showed that ctDNA analysis discovered genomic changes in genes RAS, BRAF, ERBB2, MET, and other tumor‐related genes associated with resistance to anti‐epidermal growth factor receptor (EGFR) therapy could have higher diagnostic accuracy." (PMID 36746394, 2023). "Upon examination of four IDH-mutant tumors with NE and CE samples available, we identified two IDH-mutant tumors exhibiting heterogeneous EGFR alteration, including the presence of a low allele frequency (2%) EGFR A289V gain-of-function mutation unique to the NE region in one patient tumor." (PMID 37770427, 2023). "In recent years, research on molecular mutations in non-small cell lung cancer (NSCLC) has increased our knowledge of biological pathways driving tumor development; the identification of mutations within the epidermal growth factor receptor (EGFR) gene is one such example." (PMID 37568927, 2023). "Upon disease progression during TKI therapy, clinicians may choose to do a rebiopsy of the tumor tissue for further EGFR mutation analysis, based on their judgement." (PMID 36915101, 2023). "NSCLC with mutated EGFR has lower tumor mutation burden (TMB) levels than the wild-type, which may affect PD-1 inhibitor treatment." (PMID 37033978, 2023). "Different studies have demonstrated that in ctDNA EGFR mutant patients treated with EGFR TKIs, objective response rate (ORR), progression-free survival (PFS), and overall survival (OS) are similar to that in patients with EGFR mutations detected in tumor tissue." (PMID 37445976, 2023). "These modifications could aid in the evolution of a response to targeted therapy and could also account for increases in relative tumour mutation burden (rTMB) in patients exposed to anti-EGFR leading to acquired resistance." (PMID 37569598, 2023). "One patient (D627) harbored an EGFR mutation in both the tumor tissue and the plasma sample." (PMID 37372399, 2023). "Based on the positive results of the ADAURA study, osimertinib is currently indicated for adjuvant treatment after complete tumor resection in adult patients with stage IB-IIIA NSCLC whose tumors have EGFR exon 19 deletions or exon 21 L858R substitution mutations." (PMID 37888038, 2023). "The incidence of EGFR mutations in NSCLC is dependent on tumor type and ethnic background." (PMID 38008767, 2023). "Recent medications developed for EGFR mutations have improved overall survival and tumor control, and the fact that EGFR-TKI is able to penetrate the blood–brain barrier could have a profound effect on the formulation of treatment strategies." (PMID 36676186, 2023). "Thus, the current scientific problems for the therapy of EGFR-overexpressing tumors deal with the finding of molecular markers associated with tumor sensitivity to the treatment." (PMID 38201251, 2023). "Previous studies showed that EGFR mutation status could have an effect on the response to radiotherapy, causing an impact on overall survival and tumor control." (PMID 36676186, 2023). "Similarly, the resistance of tumours with KRAS mutations to anti-EGFR therapy are well documented, rendering tumours insensitive to this chemotherapeutic agent in many cases." (PMID 38136361, 2023). "It was concluded that patient screening based on the presence of EGFR-activating mutations in the tumor could help select potential responders to gefitinib therapy." (PMID 38201251, 2023). "Internalization of membrane EGFR may disrupt EGFR-specific signaling, presenting a mechanism that may underlie the synergistic inhibition of tumor cell growth." (PMID 37762316, 2023).
tumor (continued). "However, the findings were inconsistent in the mutation sites, which revealed a single p.L858R mutation only in the tumor tissue but both EGFR p.L858R and p.T790M mutations in the plasma samples." (PMID 37372399, 2023). "However, due to tumor heterogeneity and complicated regulatory mechanism, the patients harboring uncommon EGFR mutation showed different susceptibility to icotinib." (PMID 37795433, 2023). "Circulating tumor DNA (ctDNA) can be examined for relevant mutations (such as EGFR), which may aid in determining the appropriateness of immunotherapies." (PMID 37842196, 2023). "Similarly, eccDNA not only encodes the tumor-specific and highly transcribed oncogene EGFR but also amplifies oncogenes at a higher copy number compared with those amplified by linear chromosomes." (PMID 39534571, 2023). "Moreover, aberrant EGFR signalling, activated via mutation and amplification of EGFR, or phosphorylation of EGFR tyrosine kinase, is increasingly recognised as a driver of resistance to therapies in tumours." (PMID 36672705, 2023). "In addition to a difference in tumor suppressor pathway, many pathways related to carcinogenesis and progression showed higher activity in high-risk patients, such as the EGFR pathway, MAPK pathway, and PI3K pathway." (PMID 37372358, 2023). "In addition to NGS, an immunohistochemistry (IHC)-based approach was undertaken in patients with sufficient remaining tumor samples (n = 20) to explore the association of EGFR and MET expression with tumor response." (PMID 37710001, 2023). "Less than 5% of HNSCC have EGFR mutations, which may partially explain the reported tumor resistance to TKIs." (PMID 36982894, 2023). "EGFR mutations were identified in the tumor of 16/45 patients (35.6%)." (PMID 37569332, 2023). "There exist a close relationship between mutations of KRAS and MAPK1 and the resistance of NSCLC to EGFR-TKI targeted drugs such as Gefitinib and Erlotinib, which can cause sustained activation of the EGFR signaling pathway and accelerate tumor cell proliferation." (PMID 37065830, 2023). "It was hypothesized that EGFR inhibition, via erlotinib, would enhance tumor response due to both the implicated roles of the EGFR pathway in the pathogenesis of HCC and that of EGFR activation interfering with HCC response to sorafenib." (PMID 37173972, 2023). "EGFR mutations play a crucial role in tumor aggressiveness and response to therapy in NSCLC." (PMID 36983578, 2023). "Studies have also shown that EGFR-TKI resistance can cause functional changes of tumor cells and DNA hypermethylation of tumor suppressor gene (TSG), and epigenetic intervention might be an effective strategy to reverse EGFR-TKI resistance." (PMID 36778111, 2023). "One assumption is that EGFR mutation is an early and clonal event in tumor evolution, and tumor harboring EGFR mutations seemed to act in line with “attenuated progression”, described as initial oligometastases and gradually gaining metastatic capacity over time." (PMID 37062064, 2023). "Our objective in the current study was to compare the effectiveness of surgery alone versus surgery plus adjuvant SRS to the post-surgical cavity in terms of local tumor control in cases of 1 or 2 brain metastases EGFR mutation status is also recorded and analyzed." (PMID 36676186, 2023). "However, EGFR is the most crucial drug target in tumor therapies; its mutations present an organ site asymmetry based on the origin of the organ." (PMID 38201528, 2023). "Driver and drug-resistant mutations in primary tumours with LM included: EGFR L858R (10, 35.7%), EGFR 19del (6, 21.4%), EGFR L858R+MET (1, 3.6%), EGFR L858R+S768I (1, 3.6%), ALK (2, 7.1%), ROS1 (1, 3.6%), negative (5, 17.9%), and unknown (2, 7.1%)." (PMID 38269023, 2023).
tumor (continued). "Other factors that are currently being investigated for prognostic significance in localized NSCLC include circulating tumor DNA, epigenetic alterations and tumor molecular alterations, such as epidermal growth factor receptor mutations and tumor suppressor genes mutations." (PMID 37568693, 2023). "As a result of NGS analysis, a total of 45 somatic mutations in tumor DNA and 30 somatic mutations in ctDNA were detected; it is also reported that the number of EGFR mutant alleles detected by NGS during treatment is consistent with the allele frequency determined by dPCR." (PMID 38304031, 2023). "EGFR-activating mutations were detected in the cfDNA of 20 (90.9%) of the 22 pretreatment plasma samples, and the type of activating mutation was the same as that identified in tumor tissue or plasma before study enrollment." (PMID 37686506, 2023). "Thus, by analyzing PLA staining on tumor sections, we suspected that a strong association between EGFR and Sortilin seemed to improve OS." (PMID 37576898, 2023). "However, we found a significant association with tumor grade (p = 0.031); in other words, high EGFR expression was associated with higher grade." (PMID 36769112, 2023). "The higher EGFR expression level has been associated with the advanced tumor stage." (PMID 37445686, 2023). "In a meta-analysis of 3110 patients of the diagnostic value of ctDNA vs tumour tissue, ctDNA was a highly specific and effective biomarker for the detection of EGFR mutation status, with a pooled sensitivity and specificity of 0.620 (95% CI 0.513–0.716) and 0.959 (95% CI 0.929–0.977), respectively." (PMID 37894366, 2023). "In lung neoplasms, the expression of BZW1 may be linked to tumor migration and plays a role in metastasis formation by interacting with EGFR." (PMID 37895255, 2023). "While it is unclear whether HGF activates MET in a paracrine or autocrine way, elevated tumor-stroma interactions were associated with unfavorable responses to EGFR TKI in clinical practice." (PMID 36647832, 2023). "EGFR mutation is another targetable alteration identified in these tumours." (PMID 36882456, 2023). "Therefore, approaches to target EGFR mutation to prevent tumor progression in EGFR mutated populations are an urgent need." (PMID 36875137, 2023). "Residual tumor cells may contain cancer stem cells or cells with acquired resistant mutations, which may contribute to tumor progression and EGFR-TKI ineffectiveness over time." (PMID 37046679, 2023). "However, EGFR mutations were associated with decreased tumor mutation burden compared with tumors with wild-type EGFR." (PMID 38001917, 2023). "Cancer with mutations involving the epidermal growth factor receptor may have a distinct metastasis pattern highlighting the potential role of tumor genetics in the metastasis behavior of the tumor." (PMID 37771447, 2023). "High expression of EGFR is observed in tissues from OS in association with tumor progression." (PMID 37240338, 2023). "When photosensitizer conjugation was combined with both EGFR-targeted and vascular endothelial growth factor receptor 2-targeted nanobodies, it resulted in damage to cancer cells and the destruction of tumor-associated vessels, representing an exceptionally effective approach for anti-cancer PDT." (PMID 38067344, 2023). "However, no relevant studies have yet shown the association between altered EGFR signaling pathways in tumor cells and the infiltration and activation of Bregs, especially in GBM." (PMID 37601668, 2023). "Similarly, a significant association of EGFR expression was observed with age, tumor size, tumor site, histological subtype, histological differentiation, nodal metastasis, ENE, and PNI (p < 0.05)." (PMID 37588336, 2023).
tumor (continued). "Accordingly, in one study of a representative triple-negative European population, EGFR >50% assessed in the primary tumour (n = 284) was associated with a 2-fold increase in the risk of recurrence and death (HR for 4-year DFS 2.39, 95% CI 1.32–4.34, p = 0.004 and for OS, HR 2.34, 95% CI 1.2–4.9)." (PMID 38273853, 2023). "This study showed that successful detection of the T790M mutation using plasma samples in patients with disease progression following first-line treatment with the first- or second-generation EGFR-TKI was associated with the tumor burden, including the number of metastatic organs." (PMID 36900237, 2023). "Moreover, it is also possible to find other EGFR alterations consisting of the combination of EGFR mutations with other EGFR mutations or with one or more mutations of other genes (tumour suppressor gene or oncogene)." (PMID 37376053, 2023). "It should be noted that tumor cells in which the p.Cys797Ser and p.Thr790Met variants occur together in the cis-configuration (on the same allele) were shown to be insensitive to currently approved EGFR-TKIs, including third-generation EGFR-TKIs." (PMID 36798672, 2023). "The results reported here, demonstrate that both EGFR and CD10 are poor prognosis factors since their overexpression were associated with a large tumour size, also we were able to point out that EGFR was overexpressed in patients with a high mitotic index (Ki67>50%)." (PMID 38974258, 2023). "Therefore, we also observed the detection efficacy in EGFR and main types of mutations which are very important in the tumor response to chemotherapies, targeted and immune therapies, and acquirement of resistance, by tissue- and plasma-NGS." (PMID 37004022, 2023). "ExoNA measurements may expand the utility of exosomes as a potential diagnostic and prognostic tool for EGFR-mutated cancers, as they may provide a more complete assessment of tumor progression and response to targeted therapies." (PMID 37122754, 2023). "For the common + rare and common + VUSs subtypes, the two EGFR mutations could be either in the same or in different tumor cells." (PMID 36829178, 2023). "In addition, elevated VEGF and EGFR expression was associated with nodal invasion and tumor progression." (PMID 37240178, 2023). "This supports the hypothesis that a higher tumor mutational burden (TMB) presented by EGFR-TKI acquired resistance results in an increase of immunogenic neo-antigens, in turn affects the TCR clonality of CD39 + CD8 + T cells in MPE." (PMID 38087217, 2023). "Mutated EGFR reprograms the metabolism of tumor cells through the PI3K/AKT/mTOR pathway." (PMID 36994237, 2023). "Additionally, advances in comprehensive genomic profiling have given us insights into various mutations and concurrent genetic alterations other than EGFR mutations, inducing primary resistance in the context of tumor heterogeneity." (PMID 36835536, 2023). "Circulating tumor DNA (ctDNA) testing has recently allowed the noninvasive detection of heterogeneous molecular alterations that underlie the evolution of resistance to anti-EGFR." (PMID 37434969, 2023). "EGFR mutations have been shown to promote the development and progression of various tumours." (PMID 37542324, 2023). "The EGFR signaling pathways do not only induce cell proliferation and inhibit apoptosis but are also associated with angiogenesis, with the development of an appropriate vascular network being necessary for tumor growth, invasion, and metastasis." (PMID 37194849, 2023). "Based on the current understanding of tumor heterogeneity and complex cellular signaling within the tumor and microenvironment and advances in molecular sequencing, we have identified both EGFR-dependent activating mutations and EGFR-independent mechanisms of resistance." (PMID 37675274, 2023).